ARID1A (AT-rich interaction domain 1A)
Diseases named in the same sentence as ARID1A in open-access papers (continued):
Sharing a sentence is not in itself a finding about the gene and the disease.
tumor (continued). "Using data from The Cancer Genome Atlas (TCGA) and Clinical Proteomic Tumor Analysis Consortium (CPTAC), we explored the relationship between tumors with ARID1A mutations and NRF2 signaling because ARID1A is the most frequently mutated SWI/SNF subunit." (PMID 38358974, 2024). "Loss of ARID1A cannot be compensated by increasing ARID1B expression, and in most tumor samples, the expression of ARID1B is also lower than that of ARID1A, suggesting that ARID1B is necessary for promoting tumor development in ARID1A mutations." (PMID 38365747, 2024). "Patients with high ARID1A abundance in both tumor (P = 0.007) and blood (P = 0.040) had more frequently OS < 6 months." (PMID 38378604, 2024). "Of the SWI/SNF complex members, ARID1A is the most frequently mutated in OCCC, with studies reporting between 42–67% of these tumours with somatic ARID1A mutation." (PMID 39272926, 2024). "UCA1 overexpression abolished the tumor-suppressing effects of ARID1A in vivo, confirming the in vitro results." (PMID 38534790, 2024). "The MDA-MB-468 and HCC1937 cells also displayed decreased UCA1 levels, after their exposure to another tumor suppressor, ARID1A." (PMID 38534790, 2024). "Previous studies have identified specific mutation types associated with tumor sensitivity to AURKA inhibitors, such as RB1 deficiency or loss of SMARCA4 or ARID1A." (PMID 38521813, 2024). "Together, these data indicate that heterogeneous expression of ARID1A reflects different abundance of tumor infiltrating lymphocytes." (PMID 38555560, 2024). "ARID1A has been recognized as a tumor suppressor, while disrupting the canonical SWI/SNF complex structure through the silencing of both ARID1A and ARID1B has been found to inhibit the growth and metastasis of NB." (PMID 39174852, 2024). "ARID1A serves as a critical constituent of the canonical BAF (cBAF) complex and functions as a tumor suppressor, one frequently lost through genomic mutations." (PMID 38727317, 2024). "To investigate the immunomodulatory role of ARID1A in HBV-HCC, we calculated the TMB, which was measured by the quantity of somatic mutations per Mb in the tumour genome." (PMID 38166741, 2024). "Specifically, the relationship between ARID1A loss/mutation, clinical characteristics, outcomes, CD8+ tumor-infiltrating lymphocytes (CD8+TIL), and DNA mismatch repair deficiency (MMRD) revealed ARID1A gene inactivation in 42% of OCCC and 25% of OEC." (PMID 38725626, 2024). "ARID1A mutations are linked to larger and moderately differentiated HCC tumours, metastasis and poor prognosis (Refs 143, 144)." (PMID 39320855, 2024). "Deletion of specific complex factors, such as Arid1a or Brg1, can promote tumor development, although their role in cancer is multifaceted." (PMID 38474109, 2024). "In OS, Arid1a has been found to exhibit a tumor-suppressive function both in cell lines and human samples, where its loss associates with a worse prognosis." (PMID 39123453, 2024). "Tumours in which both ARID1A and ARID1B are mutated are reported to retain a wild-type allele of ARID1B, providing evidence that a certain level of wild-type ARID1B is essential to avoid synthetic lethality in ARID1A-mutant tumours." (PMID 39272926, 2024). "In preclinical models, ATRi kills tumor cells with loss of ataxia telangiectasia mutated (ATM), AT-rich interactive domain-containing protein 1A (ARID1A), and specific components of the DDR pathway or those driven by oncogenes such as cyclin E and Myc." (PMID 37934611, 2024).
tumor (continued). "Another scRNA‐seq result showed that 21 vital tumour mutant genes were identified in bladder cancer samples, with mutations in ARID1A, GPRC5A and MLL2 increasing the self‐renewal capacity of tumour cells and contributing to tumorigenesis." (PMID 38520221, 2024). "Several studies have shown that inactivation of ARID1A can affect the biological functions of tumor cells, such as proliferation, metastasis, differentiation, apoptosis, and drug sensitivity, and is closely related to the clinical prognosis of tumors." (PMID 39697230, 2024). "ARID1A is generally considered to be a tumor suppressor gene that can inhibit the biological behavior of malignant tumors and regulate the cell cycle to promote apoptosis to exert its anticancer effects." (PMID 38893181, 2024). "Consistent with previous reports, we confirmed the tumour-suppressive effect of ARID1A using bioinformatics approaches and preclinical experiments." (PMID 38166741, 2024). "IHC staining of these tumours additionally revealed that the loss of ARID1A significantly upregulated CD8 and CD56 infiltrating levels in these tumours." (PMID 38166741, 2024). "Another epigenetic regulator frequently dysregulated in UC (18–25%), ARID1A, has not only shown altered signal transduction in other cancers, but also altered cell cycle control, DNA damage repair responses, tumor microenvironment and checkpoint signaling." (PMID 38540132, 2024). "More specifically, a correlation between ARID1A deletion and critical clinico-pathological parameters including tumor differentiation, lymph node metastasis, and tumor size has also been demonstrated." (PMID 38893181, 2024). "Using the same strategies of targeting mutant SWI/SNF, the HDAC6 inhibitor ACY1215 combined with anti-PD-L1 antibody reduced tumour burden and eliminated ascites in an in vivo model of ARID1A-inactivated OCCC." (PMID 39272926, 2024). "We assessed ARID1A expression and tumor-infiltrating lymphocytes (CD8+) and immune checkpoint molecules (PD-L1/PD-1) using immunostaining and MSI analysis." (PMID 38893118, 2024). "ARID1A deficiency impaired DNA damage repair (DDR), resulting in increased mutagenesis in tumor cells and activation of the adaptive immune response." (PMID 38555560, 2024). "Generally, ARID1A has been identified as a specific tumor suppressor in CRC, and variations of ARID1A have been reported to be correlated the tumorigenesis and the poor prognosis of CRC." (PMID 38555560, 2024). "Previous studies on cell line and tumor tissues have also shown a similar pattern, suggesting that Arid1a serves as a tumor suppressor in OS cell lines." (PMID 39123453, 2024). "In this study, patients with heterogeneous ARID1A expression in the primary tumor showed different lymph node metastases staining patterns as diverse as complete loss of ARID1A (53.2%), retained expression (21.3%), and heterogeneous expression (25.5%)." (PMID 38893181, 2024). "Glutathione (GSH), as a major intracellular antioxidant, protects tumor cells from reactive oxygen species (ROS) attack, while abnormal GSH metabolism is considered to be one of the characteristics of ARID1A-deficient OCCC cells." (PMID 38347608, 2024). "Given the high mutation rate of ARID1A in several cancers, it is of clinical importance to know whether ARID1A loss correlates with the accumulation of unrepaired DNA damage, the level of immune regulatory cytokines, and the levels of tumor-infiltrating immune cells." (PMID 38587186, 2024). "Our results implicate ARID1A inactivation in promoting tumor progression and survival of HPV- HNSC through activation of the KEAP1-NRF2 signaling pathway." (PMID 38358974, 2024).
tumor (continued). "As an example, SMARCA4 loss accelerates tumor progression and promotes lung adenocarcinoma (LUAD) dedifferentiation, while abrogation of another key SWI/SNF component, Arid1a, suppresses tumor initiation and metastasis in hepatocellular carcinoma." (PMID 39080761, 2024). "It is however of clinical importance to use ARID1A expression as a potential biomarker that correlates with the level of immune regulatory cytokines, and hence can estimate the levels of tumor-infiltrating immune cells." (PMID 38587186, 2024). "Mutations in mSWI/SNF subunits including ARID1A/B, BRG1, and SS18 are linked to multiple tumor types." (PMID 38326345, 2024). "AT-rich interaction domain 1A (ARID1A) mutant tumors show active anti-tumor immune response, which is the potential indication of immunotherapy." (PMID 38555560, 2024). "ARID1A exerts tumor-suppressive effects by regulating various cellular activities, such as cell cycle evolution, cell proliferation, DNA damage repair, and mitochondrial oxidative stress." (PMID 38835016, 2024). "DepMap also predicts an opposing function for SWI/SNF component ARID1A, which appears as a slight dependency in contrast to its apparent function as a tumor suppressor in PDAC57." (PMID 36653361, 2023). "There is evidence showed that Arid1a‐mediated gene regulation plays an important role in anti‐tumour and damage regeneration." (PMID 36916004, 2023). "Previously, ARID1A was considered a critical suppressor of cancer progression in gastric, pancreatic, and other cancers, suggesting that ARID1A-inhibited tumour development is universal." (PMID 37173914, 2023). "The present study demonstrated that downregulated or mutated ARID1A attenuates DNA HRR through stimulation of the PI3K/Akt1 pathway and makes tumor cells highly sensitive to PARPi and PARPi/ionizing radiation (IR) combination." (PMID 36910637, 2023). "ARID1A regulates gene transcription, DNA binding, homologous recombination, tumor suppression, DNA damage response, and steroid receptor signaling." (PMID 37686496, 2023). "As an alternative experiment to the orthotopic transplantation tumour model, the vein model was used in this study to assess the regulatory effect of ARID1A on TNBC cell metastasis ability by simulating the second half of the metastasis process." (PMID 37173914, 2023). "Targeting complementary pathways that will try to compensate for ARID1A failure is a possibility to provide a synthetic lethal effect in those tumor cells." (PMID 37627124, 2023). "ARID1A is indeed mainly localized as enhancers of tumor cells acting as a cofactor at regions bound by AP1 transcription factors, which act downstream in the MEK/ERK pathway." (PMID 36658200, 2023). "During tumour initiation, ARID1A is proto-oncogenic, and promotes tumour formation by upregulation of cytochrome P450 proteins and generation of reactive oxygen species." (PMID 38275587, 2023). "ARID1A, also known as AT-rich interactive domain-containing protein 1A, is a tumor suppressor gene located on chromosome 1p36.11." (PMID 37958970, 2023). "Ongoing investigations are actively exploring how ARID1A operates in tumour suppression and its intricate interactions with other oncogenic networks." (PMID 38041544, 2023). "Ever since the discovery as a tumor suppressor for ARID1A, synthetic lethal phenotypes have been uncovered in ARID1A-deficient cells when treated with PARP inhibitors, ATR inhibitors, EZH2 inhibitors, and other emerging agents." (PMID 36980292, 2023). "We also found that ARID1A was commonly altered in BC, NSCLC, CRC and OC and that TMB-high tumours were enriched with ARID1A GAs." (PMID 37821580, 2023). "The mutation landscape of HRR-related genes revealed several possible recurrent hotspot driver mutations in ARID1A, ATRX, ATM, and BRCA1/2, including R1989* in ARID1A, which was carried by over 30 tumor patients." (PMID 37264024, 2023).
tumor (continued). "Some studies report that ARID1A exerts cancer initiation and progression activities in specific cancer types, generally solid tumors, but its function as tumor suppressor or oncogene remains an open question." (PMID 36890819, 2023). "This study demonstrates that Arid1a is required for the maintenance of active enhancers in genes involved in the tumor suppressor pathway, providing new mechanistic insight into the epigenetic regulation of GC." (PMID 36653445, 2023). "They observed that ARID1A depletion resulted in accelerated tumor growth and decreased survival in vivo, while ARID1A overexpression had the opposite effect, increasing survival and slowing tumor growth." (PMID 36890819, 2023). "The proinflammatory cytokine interleukin 6 (IL-6) was overexpressed in OCCC with concurrent ARID1A deletion and PIK3CA mutation, and the cytokine promoted tumour cell growth and survival." (PMID 38275587, 2023). "For example, ARID1A can regulate the immune response by modulating the interferon-responsive gene methylation profile in multiple tumor types." (PMID 36890819, 2023). "Since ARID1A has taken a central role in tumorigenesis and in many different tumor entities over the last years, it is of importance that quantitative methods are optimized and validated before making their way into clinical application." (PMID 37627124, 2023). "Since ARID1A is regarded as an important tumor suppressor in EMC, the effects of PPARα silencing and activation on the expression of ARID1A were examined." (PMID 37305395, 2023). "Next, we generated YAP knockdown (YAPKD), ARID1A knockout, and double knockdown cells (ARID1A/YAPDKO) to verify the role of YAP in ARID1A-associated EMT and tumour metastasis." (PMID 37173914, 2023). "A recent report among 71,301 patients suggests that liquid biopsies identified ARID1A alterations at a frequency similar to that found in primary tumor material." (PMID 37711591, 2023). "We believe that our suggested method ensures a high reproducibility and can be used for a high sample throughput to determine the ARID1A concentration in different tumor entities." (PMID 37627124, 2023). "PIK3CA coexisted with only two of the four ARID1A mutant cases, and it would be interesting to further study the codependency of these two genes in tumor formation." (PMID 37465112, 2023). "A four-gene panel consisting of ARID1A, CTNNB1, FBXW7 and PPP2R1A was used to investigate mutations in gynaecologic tumour tissue." (PMID 36982928, 2023). "The landscape of methylation in HRR-related genes also revealed an abnormal methylation signature of HRR-related genes such as ARID1A, whose methylation levels were significantly higher in tumor tissues compared to normal tissues." (PMID 37264024, 2023). "AT‐rich interaction domain 1A (ARID1A) is one of the subunits of the BRG1‐ or HBRM‐associated factor complex and has been demonstrated to have tumor suppressor effects." (PMID 37215622, 2023). "ARID1A nuclear expression was inversely related to tumor size (p = 0.006), pathology grade (MCp = 0.046), and post-microwave ablation tumor recurrence (FEp = 0.041) among patients with BCLC stages 0/A eligible for ablation." (PMID 37686496, 2023). "Here, we present an enzyme-linked immunosorbent assay (ELISA) to quantitatively measure ARID1A levels in tumor tissue or cell culture lysates." (PMID 37627124, 2023). "This comprehensive review aims to shed light on how ARID1A's inadequacy affects genome stability, its role in shaping the tumour's immune environment and explore potential interactions with ICI therapy in the context of GC." (PMID 38041544, 2023). "Loss of ARID1A is associated with mismatch repair defects, high mutant load, high PD-L1 expression, high MSI, and an increased number of tumor-infiltrating lymphocytes in many cancers." (PMID 36873929, 2023). "Using additional matched tumor pair analysis, mutations in TRAF7, ARID1A, and ERBB3 were identified as subclonal driver events at the time of recurrence." (PMID 38073632, 2023).
tumor (continued). "Inactivation of ARID1A is known to impair T‐cell infiltration into tumours and reduce anti‐tumour immunity." (PMID 38041544, 2023). "In summary, we demonstrated that ARID1A mutation stimulates PI3K/Akt1 pathway, attenuates DNA HRR, and makes tumor cells highly sensitive to PARPi and PARPi/IR combination." (PMID 36910637, 2023). "Even epigenetic changes are involved in this tumor biology, such as key mutations in chromatin remodeling (MERC1, SMARCA2, ARID1A, ARID1B, SMARCA4) and an imbalance in miRNAs (miR-155, miR-320a, miR-99a, miR-205) that regulate gene expression." (PMID 37476370, 2023). "Studies have shown that ARID1A has a crucial role in regulating gene expression that drives oncogenesis or tumor suppression and that deletion of ARID1A promotes tumor progression." (PMID 37981695, 2023). "Previous studies have shown that YAP can form a complex with BRG1 and affect tumour progression, both ARID1A and BRG1 are components of the SWI/SNF complex." (PMID 37173914, 2023). "Depletion of ARID1A resulted in downregulation of exhaustion-related genes in tumor-infiltrating T cells through limiting the acquisition of exhaustion-associated chromatin accessibility." (PMID 36980292, 2023). "In the population of patients being offered an NGS test for their advanced tumor, we found 9% of ARID1A+ cancers, a percentage comparable to that reported in the literature (6%)." (PMID 37711591, 2023). "Xenograft mice having ARID1A tumors show a drastic decrease in tumor burden upon combined radiation and PARP inhibitor treatment." (PMID 37093326, 2023). "For example, inhibition of Arid1a epigenetic modification improves the anti‐tumour activity of CD8T cells, damages organ regeneration, and leads to organ disorders." (PMID 36916004, 2023). "In the present work, we have demonstrated that downregulated or mutated ARID1A attenuates DNA HRR by stimulating the PI3K/Akt1 pathway and renders tumor cells highly sensitive to PARPi." (PMID 36910637, 2023). "Its tumor suppressor function is more well researched, with ARID1A inactivation resulting in tumor initiation in PTEN- or PIK3CA-mutant cells in gynecological malignancies and hypermutated/MSI-type cells in colon cancer." (PMID 37109525, 2023). "Attenuation of DNA HRR in ARID1A-mut tumor cells sensitizes them to PARPi and PARPi/IR combination by a mechanism of synthetic lethality." (PMID 36910637, 2023).